TIGIT (T cell immunoreceptor with Ig and ITIM domains)
Diseases named in the same sentence as TIGIT in open-access papers (continued):
Sharing a sentence is not in itself a finding about the gene and the disease.
tumor (continued). "As cytolytic effector cells, NK cells are involved in the release of tumor antigens, and the regulation of NK cell function by TIGIT significantly impacts the initial phase of the cancer immune cycle." (PMID 40356928, 2025). "Interaction of TIGIT with PVR or PVRL2 on tumour cells leads to the inhibition of immune cells via the immunoreceptor tyrosine-based inhibitory motif (ITIM) domain." (PMID 40317320, 2025). "TIGIT is expressed on tumor-reactive T cells, NK cells, DCs, and macrophages, where it impedes antitumor activation and immune functionality." (PMID 40677703, 2025). "Tumor-infiltrating Tregs expressed high levels of cell surface molecules associated with T-cell activation, such as CTLA4, PD-1, LAG3, TIGIT, ICOS, and TNF receptor superfamily members." (PMID 40092987, 2025). "It has been shown that TIGIT plays an important role in the regulation of tumor identification in T-cells both in vivo and in vitro." (PMID 40075698, 2025). "TIGIT is a suppressor receptor shared by T and NK cells that suppresses tumor cell killing by NK and T cells." (PMID 39910672, 2025). "For instance, upregulation of inhibitory receptors such as PD-1 and TIGIT and tumor-driven immune evasion strategies can stifle NK cell cytotoxicity." (PMID 40281554, 2025). "Overall, our results reveal a prevalence of NK and CD8+ T-cells with an increased expression of PD-1, TIM-3, LAG-3, and TIGIT on their surface in tumor-rich niches." (PMID 40227595, 2025). "In mice injected with EMT-6 BC cells, the concurrent inhibition of TIGIT and PD-1 triggered robust anti-tumor immune responses, resulting in a CR." (PMID 40281554, 2025). "In DLBCL-type RT, CD226, a TIGIT competitor that activates T and NK cells via CD155, is abnormally elevated, suggesting an imbalance favoring activating signals in DLBCL-type RT tumor cells, contrasting with higher TIGIT levels in CLL cells." (PMID 40075754, 2025). "TIGIT acts as a co-inhibitory receptor that indirectly inhibits immune cells and suppresses the immune response against tumours." (PMID 40759637, 2025). "Understanding how TIGIT modulates NK cell activity opens new avenues for immunotherapeutic strategies, particularly in overcoming tumor-induced immune suppression." (PMID 40299429, 2025). "CD155, the primary ligand for TIGIT, is found on tumor‐infiltrating myeloid cells and is upregulated on tumor cells, which facilitates local immune surveillance suppression." (PMID 40551477, 2025). "Tumor-infiltrating lymphocytes (TILs) were reported to express significantly higher levels of TIGIT than peripheral T cells." (PMID 40890162, 2025). "A study found that TIGIT expression on activated NK cells enhances their anti-tumor function; however, chronic TIGIT engagement by its ligand PVR induces dysfunction." (PMID 40567374, 2025). "In this study we show that CD155 immune checkpoint is expressed in all MB subgroups and that interfering with the CD155/TIGIT axis using anti-TIGIT Tiragolumab potentiates MB tumor cell killing by NK cells." (PMID 40703802, 2025). "The blockade of TIGIT has been shown to prevent NK cell exhaustion and enhance their anti-tumor immunity." (PMID 40367012, 2025). "TIGIT also plays a role in tumor immunopathology by inducing T-cell exhaustion, as evidenced by reduced proliferation, decreased cytokine production, and diminished antitumor functionality." (PMID 40567374, 2025). "Blocking TIGIT with monoclonal antibodies has emerged as a promising strategy to restore anti-tumor immunity." (PMID 40739089, 2025). "Given its aberrant expression in tumors and the critical role of the CD155/DNAM-1/TIGIT axis in tumor progression and immune regulation, targeting CD155 has emerged as a promising therapeutic strategy." (PMID 40478751, 2025). "Targeting TIGIT has demonstrated potential in reinstating anti-tumor immunity and inhibiting BC metastasis." (PMID 40177538, 2025).
tumor (continued). "While T cells are the primary source of TIGIT expression, stellate, epithelial and endothelial cells also have increased expression in the tumour compared to pancreatic adjacent normal tissue." (PMID 39915477, 2025). "Several studies have demonstrated that TIGIT is an inhibitory receptor shared by T cells and NK cells, capable of suppressing the cytotoxic effects of NK and T cells against tumor cells, and it represents a novel target for immunotherapy." (PMID 40018995, 2025). "Targeting inhibitory receptors like TIGIT and PD-1 holds great potential for enhancing NK cell activity and counteracting tumor-induced immune evasion." (PMID 40299429, 2025). "The section concludes with experimental evidence that tumor cells drive TIGIT upregulation, supporting its functional role in T cell exhaustion." (PMID 40799645, 2025). "TIGIT is a crucial target in tumor immunotherapy, as it can prevent NK cells from releasing tumor antigens, impair dendritic cell-induced T cell priming, or inhibit CD8+ T cell-mediated killing of cancer cells." (PMID 40165902, 2025). "Analysis of RNA-sequencing data revealed that TIGIT mRNA expression was significantly elevated in tumor tissues compared to matched adjacent normal tissues in various of tumors." (PMID 40799645, 2025). "Co-blocking of TIGIT and IL1β activated anti-tumor immunity, inhibited bone metastasis of BC, and improved the survival rate." (PMID 41181119, 2025). "Other inhibitory checkpoints implicated in NK cell tumor immunity include LAG-3, NKG2A, TIM-3, and TIGIT." (PMID 40849493, 2025). "TIGIT prevents tumor cell killing by NK cells and cytotoxic T cells and enhances the immune suppressive activity of regulatory T cells through the combination with its legends." (PMID 40236710, 2025). "Bottom) Schematic illustration of anti-tumour immune response at the cellular level induced by anti-PD-1/TIGIT checkpoint blockade for efficient cancer immunotherapy." (PMID 39939955, 2025). "Acquired resistance, on the other hand, can develop during treatment due to adaptive immune evasion, such as upregulation of alternative immune checkpoints (e.g., LAG-3, TIGIT) or depletion of effector T cells in the tumor microenvironment." (PMID 40299523, 2025). "In the patient-derived xenograft (PDX) model, the anti-TIGIT treatment group demonstrated reduced tumor weight, enhanced CD8 frequency, and an increased IFN-γ proportion compared to the PBS treatment group." (PMID 39939322, 2025). "Several gene signatures (FOXP3, Helios, neuropilin-1, CTLA-4, PD-1 and LAG-3) are also found to be upregulated in TIGIT+ Tregs within the tumor microenvironment (TME), turning Tregs to a more immunosuppressive phenotype." (PMID 40890162, 2025). "This suggests that co-blockade of PD-1 and CTLA-4 facilitates the entire process of T cells from activation to exercise of effector functions, whereas co-blockade of PD-1 and TIGIT provides enhanced tumor killing by activated T cells." (PMID 40890162, 2025). "While TIGIT blockade aims to reinvigorate exhausted effector T cells to boost anti-tumor immunity, its presence on Tregs and NK cells introduces competing effects." (PMID 40567374, 2025). "Binding to CD155, TIGIT suppresses the function of T cells and natural killer (NK) cells, particularly within the tumor microenvironment (TME), where this immunosuppressive axis represents a critical mechanism driving tumor immune evasion." (PMID 40747615, 2025). "Dual therapy with anti-PD-1 and anti-TIGIT significantly improved survival, enhancing effector T cell function and reducing suppressive Tregs and tumor-infiltrating dendritic cells (TIDCs)." (PMID 40223940, 2025). "TIGIT is a newly identified ICP that significantly contributes to tumor immune evasion, and its blockade by mAbs offers a promising treatment approach for cancer." (PMID 41233805, 2025).
tumor (continued). "TIGIT-induced NK cell depletion and the capacity to impede tumor progression by blocking TIGIT corroborate the assertion that the TIGIT-induced NK cell inhibitory axis is prominent in human cSCC." (PMID 40352926, 2025). "In a humanized immune cell-reconstituted mouse model, TIGIT blockade was further evaluated for its effects on tumor growth and T cell exhaustion." (PMID 41419632, 2025). "Dual blockade of TIGIT and PD-1 in preclinical models has been found to enhance the antitumor immune response and improve tumor control." (PMID 39847233, 2025). "TIGIT expression levels also correlate with poor prognosis in many tumors, suggesting an important role in tumor progression, invasiveness, and/or metastasis." (PMID 40890162, 2025). "Dysregulated expression of TIGIT and its family molecules on NK cells contributes to NK cell dysfunction and promotes tumor immune escape in DLBCL." (PMID 40231264, 2025). "In particular, TIGIT competes with CD226 for binding to ligands expressed on tumor cells and antigen-presenting cells (APCs)." (PMID 41303538, 2025). "In mouse models, TIGIT blockade reduces tumor growth, increases CD4+ and CD8+ T cell infiltration, and reverses T cell exhaustion." (PMID 41514917, 2025). "Experimental data reveal a significant correlation between elevated TIGIT expression levels and NK cell dysfunction in tumor-bearing mice and CRC patients." (PMID 40463500, 2025). "Our study demonstrates a significant increase in CD8 + memory T cell tumour infiltration in response to the combination of anti-PD-1 and anti-TIGIT, especially after the second dose, where the memory T cell population reaches its highest level." (PMID 39939955, 2025). "Recently, increased expression of TIGIT has been shown on regulatory CD4+ T cells of primary tumor tissue as well as during chronic infections." (PMID 40274631, 2025). "We observed a significant difference (p = 0.02) in PD-L1/TIGIT co-expression in tumor-infiltrating cells from patients with triple-negative tumors (33.3%) compared to patients with Luminal A (10.5%), Luminal B (20.0%) and Her2+ (12.5%) tumors." (PMID 40565313, 2025). "TRM cells coexpressing PD‐1 and TIGIT in PDAC tumors are associated with better prognosis; tumor infiltration by TRM cells is linked to an enhanced response to immunotherapy." (PMID 39802636, 2025). "Previous research has largely focused on the role of CD155 in tumor immune evasion through the CD155/DNAM-1/TIGIT axis, with less attention on its potential as a direct therapeutic target." (PMID 40478751, 2025). "Current research on the TB‐associated tumor microenvironment focuses on the PD‐1/PD‐L1 axis; however, the expression patterns of other immune checkpoints, such as TIM‐3, LAG‐3, and TIGIT, and their relationship with T‐cell depletion, remain underexplored." (PMID 40347011, 2025). "TIGIT expression is influenced by the tumor metabolic microenvironment, with glucose deprivation and TGF-β signaling promoting its upregulation." (PMID 41394868, 2025). "The blockade of TIGIT aims to restore anti-tumor immunity by enhancing both T-cell and NK-cell responses." (PMID 40806636, 2025). "Conversely, pathogenic microbes like Fusobacterium nucleatum employ mechanisms such as the Fap2 protein, which engages inhibitory receptors (e.g., TIGIT) on immune cells, creating immune-privileged tumor microenvironments and facilitating tumor immune evasion." (PMID 41245267, 2025). "Specifically, IL-17 signaling has been shown to regulate the expression of CD70 and CD80 in antigen-presenting cells while promoting TIGIT-mediated suppression in the tumor microenvironment, depending on cytokine context." (PMID 40565233, 2025). "TIGIT overexpression in CD8+ and CD4+ T cells is correlated with HNSCC progression and a poor treatment response, and TIGIT/PD-1/LAG-3 axis activation is correlated with tumor progression and the development of an immunosuppressive microenvironment." (PMID 40805285, 2025).
tumor (continued). "BsAbs not only achieved co-blockade of TIGIT and PD-1, but also bridged the gap between immune or tumor cells, which will further facilitate the immune response." (PMID 40890162, 2025). "By inhibiting TIGIT, Tiragolumab enhances T cell-mediated anti-tumor immunity, particularly when combined with programmed cell death-1 (PD-1) and programmed death-ligand 1 (PD-L1) inhibitors." (PMID 40567374, 2025). "This suggests that a CD8 + T cell-mediated anti-tumour response is potentiated by the combination of anti-PD-1 and anti-TIGIT treatment." (PMID 39939955, 2025). "Blockade of TIGIT improved NK cell function, enhancing tumor-specific T cell immunity and tumor control in syngeneic melanoma and colon cancer models." (PMID 40849493, 2025). "TIGIT engages with CD155/CD112 on tumor cells and APCs, inhibiting T-cell activity, and anti-TIGIT mAbs like vibostolimab demonstrate modest ORRs of 5–7% either as monotherapy or in combination with pembrolizumab in anti-PD-1-refractory NSCLC." (PMID 41239350, 2025). "This reduced PD-1+LAG3+TIGIT+ phenotype was maintained after subsequent re-challenges with ACHN tumor cells." (PMID 40519930, 2025). "In tumor cells, TIGIT is co-expressed with PD-1 on tumor antigen-specific T cells and tumor-infiltrating lymphocytes." (PMID 40565299, 2025). "On the other hand, preclinical studies have demonstrated that TIGIT blockade enhances anti-tumor T cell responses, reduces tumor growth, and restores CD8+ T cell potency, particularly when combined with PD-1 or PD-L1 inhibitors." (PMID 41233805, 2025). "By inhibiting CD226 signaling, TIGIT suppresses T cell and natural killer (NK) cell functions, contributing to the tumor’s immune evasion." (PMID 39857682, 2025). "Taken together, these findings support the notion that combination treatment with PRMT5i, CPT‐11, and TIGIT facilitates tumor growth inhibition and represents a novel intervention strategy for MSS CRC." (PMID 40344511, 2025). "TIGIT knockout studies have reported a reversal of T and NK cell exhaustion coupled with enhanced anti-tumor immunity." (PMID 40890162, 2025). "Strikingly, all mice responded to treatment with PD-1 and TIGIT co-blockade, with 9 out of 10 mice remaining tumour-free for over 300 days." (PMID 39939955, 2025). "In comparison, TIGIT mAb-treated mice exhibit higher frequencies of tumour-infiltrating CD8+ T cells expressing IL2/TNF-α/IFN-γ and CD4+ T cells expressing IL2, without altering the ratio of memory CD4+ T cells." (PMID 40994140, 2025). "TIGIT also binds poliovirus receptor-related protein 4 (PVRL4 or Nectin-4), a TIGIT-specific ligand recently known to be expressed on tumor cells." (PMID 40274631, 2025). "CD155 expression in tumor tissue, as well as TIGIT expression in peripheral blood/TILs, TMB and TME immunological profile can be considered when selecting biomarkers." (PMID 40890162, 2025). "Blockade of TIGIT inhibited NK cell depletion and promoted NK cell-mediated tumor immunity across many mouse tumor types." (PMID 40567374, 2025). "DNAM-1-mediated cytotoxic activity in NK cells is regulated by a multifaceted molecular network, wherein NKG2D suppresses DNAM-1-mediated cytotoxicity, and TIGIT up-regulation amplifies this inhibitory effect, consequently promoting tumor immune evasion." (PMID 40463500, 2025). "TIGIT downregulates T cell and natural killer (NK) cell function by interacting with CD-155 on antigen-presenting cells and tumor cells." (PMID 40076561, 2025). "Overcoming tumor immune evasion involves blocking inhibitory receptors (e.g., TIGIT, PD-1, and NKG2A) and targeting suppressive tumor metabolites to enhance NK activation." (PMID 41008790, 2025). "It binds to its ligands CD155 (PVR) or NECTIN-2 (CD112), which are frequently overexpressed on malignant or antigen-presenting cells (APCs), TIGIT suppresses cytotoxic immune responses, contributing to immune evasion within the tumor microenvironment (TME)." (PMID 40799645, 2025).
tumor (continued). "Tumor cells can continue to suppress immune activation when TIGIT is inhibited, thereby limiting the efficacy of existing ICI therapy." (PMID 40361336, 2025). "The expression of T cell immunoreceptor with immunoglobulin and ITIM domain (TIGIT) in SCC and AC was inconsistent, with one study reporting higher expression in SCC, whereas another found higher expression of TIGIT in AC tumours." (PMID 40639721, 2025). "The bifunctional adhesin Fap2 has been demonstrated to adhere to cancer cell-specific Gal-GalNAc-moieties while also deactivating tumor-infiltrating lymphocytes (TILs) through the immune cell receptor TIGIT." (PMID 40198705, 2025). "Inhibition of TIGIT has exhibited the reversal of cytotoxic T lymphocyte-mediated antitumor immunity depletion, curbing tumor progression in preclinical models." (PMID 39939322, 2025). "There are evidence suggesting that TIGIT synergizes with PD‐1 and impairs anti‐tumor responses in cooperation with TIM‐3." (PMID 40243372, 2025). "Cell communication analysis revealed that, in the TME, TR CD8 + T cells’ TIGIT signaling pathway frequently interact with those of other cell types, especially epithelial cells in tumor tissues." (PMID 40855305, 2025). "TIGIT as a critical immune checkpoint, capable of impairing multiple stages of the cancer immunity cycle and inhibiting effective anti-tumor responses." (PMID 40944710, 2025). "Depletion of NK cells mitigated anti-TIGIT–mediated tumor suppression and attenuated anti-TIGIT–mediated inhibition of myeloid bias." (PMID 40111422, 2025). "Collectively, these findings support the coordinated expression of the TIGIT/PVR and PD-1/PD-L1 pathways in ESCC tumor tissues and identify high expression of TIGIT/PVR as a poor prognostic marker in patients with ESCC." (PMID 39847233, 2025). "Increased expression of TIGIT in a variety of tumours, including melanoma, acute myeloid leukaemia, oesophageal SCC, neuroblastoma and HNSCC, is closely associated with tumour progression." (PMID 40994140, 2025). "Autologous CD8+ TILs, isolated from patient tumour tissues, were cocultured with the PDOs and subsequently treated with IL‐15, anti‐TIGIT, or their combination." (PMID 38279870, 2024). "Recently, focal adhesion kinase (FAK) was reported to function in tumor immunosuppression of ovarian cancer via the PVR/TIGIT pathway." (PMID 39156900, 2024). "Similar to the PD‐1/PD‐L1 axis, TIGIT exerts an immunosuppressive effect in tumor immune surveillance, thereby promoting the progression of HCC." (PMID 39540362, 2024). "Research has demonstrated that the TIGIT inhibitor tiragolumab activates the anti-tumor activity of T cells and NK cells by inhibiting the binding of TIGIT to poliovirus receptors." (PMID 39221244, 2024). "The high expression of TIGIT reduces the functionality of Tregs, thereby decreasing their immunosuppressive effects and promoting the anti-tumor actions of other immune cells in the colorectal cancer (CRC) immunological microenvironment." (PMID 39227959, 2024). "The expression levels of CD47 and TIGIT in tumor tissues (n = 115) were significantly higher than those in normal brain tissues (P = 0.0073, P = 0.0064)." (PMID 38404571, 2024). "For example, F. nucleatum can inhibit the attack of natural killer (NK) cells on tumor cells by binding TIGIT (T cell immunoglobulin and ITIM domain), an inhibitory receptor on human NK cells and various T cells via the fusobacterial Fap2 protein." (PMID 39229258, 2024). "Remarkably, the classic nonsteroidal anti-inflammatory drug aspirin was found to elicit an anti-tumor effect by reducing the expression of TIGIT." (PMID 38229100, 2024). "This suggests that IL‐15 stimulation in combination with TIGIT blockade can greatly augment the activity of preexisting tumour antigen‐specific CD8+ T cells and promote tumour‐specific immune responses." (PMID 38279870, 2024).